GPNMB (glycoprotein nmb)
Diseases named in the same sentence as GPNMB in open-access papers (continued):
Sharing a sentence is not in itself a finding about the gene and the disease.
neurodegenerative disease (27 papers, 2018 to 2025). A disorder of the central nervous system characterized by gradual and progressive loss of neural tissue and neurologic function. "Genes linked to neurodegenerative diseases, such as GPNMB, GBA, CD33, and TREM2, were downregulated in ALI‐CO‐iMG 60d compared with 60d iMG." (PMID 41221983, 2025). "GPNMB is also elevated in the substantia nigra of patients with PD, a neurodegenerative disease increasingly linked to lysosome dysfunction." (PMID 40200337, 2025). "A number of neurodegenerative diseases, including PD, are associated with an increase in GPNMB levels in the brain." (PMID 37947613, 2023). "GPNMB expression has been associated with different neurodegenerative diseases such as FTD, AD, and parkinsonism." (PMID 36618392, 2022). "Moreover, the molecular mechanisms underlying GPNMB-mediated functions in neurodegenerative diseases have been well studied." (PMID 34735454, 2021). "However, more research to elucidate the precise role of GPNMB in the inflammatory responses associated with neurodegenerative diseases is clearly required." (PMID 30340518, 2018). "Prior work demonstrated a neuroprotective role for GPNMB in SOD1-G93A mice as well as other neurodegenerative disease models." (PMID 40700130, 2025). "Several ALS-increased DEGs had previously been recognized as markers for microglia phenotypes detected in other neurodegenerative diseases (e.g., GPNMB, APOE, LTA4H)." (PMID 40700130, 2025). "Here, we show that during AE, CNS phagocytes exhibit elevated expression levels of GPNMB, a surface marker previously recognized as a constituent of a microglial signature enriched in neurodegenerative diseases." (PMID 40278930, 2025). "The main objective of this review was to present the current biological knowledge on PGRN and GPNMB interactions within the context of neuroinflammation and neurodegenerative disease." (PMID 38037070, 2023). "GPNMB can have neuroprotective effects in mitigating the effects of harmful protein aggregates, a common feature in many neurodegenerative diseases." (PMID 37744396, 2023). "An increase of GPNMB levels in the brain has also been detected in a diverse number of neurodegenerative diseases (in vitro, in vivo, and patients) such as AD, ALS and PD." (PMID 34054862, 2021). "Cross-Disease Insights: Lessons from GPNMB’s role in neurodegenerative diseases, such as its neuroprotective interaction with CD44, might inspire therapies for brain metastases." (PMID 41180454, 2025). "But GPNMB also seems to have a protective function in neurodegenerative diseases." (PMID 37947613, 2023). "In addition to being highly expressed, GPNMB seems to have a protective role in neurodegenerative diseases." (PMID 34054862, 2021). "These evidences indicated that GPNMB could serve as an emerging target for neurodegenerative diseases." (PMID 32983228, 2020). "Therapeutic approaches modulating GPNMB function might raise potential treatments for neurodegenerative diseases." (PMID 31627485, 2019). "However, the reason for and the effects of these GPNMB increases in these diseases is still unknown and has important implications for approaches aimed at targeting GPNMB as a therapy in neurodegenerative diseases." (PMID 40200337, 2025). "This perspective is beginning to be adopted by the field with respect to genes implicated in the endolysosomal system including leucine-rich repeat kinase (LRRK2), progranulin (GRN), and glycoprotein non-metastatic B (GPNMB) as risk genes for several neurodegenerative diseases." (PMID 38883776, 2024). "In addition, one study found that overexpression of GPNMB could protect against neurodegeneration changes induced by neurotoxins, indicating that GPNMB could serve as an emerging target for neurodegenerative diseases." (PMID 32983228, 2020).
neurodegenerative disease (continued). "Additionally, the presence of CD44 on other cell types, including dopamine neurons and microglia, suggests that GPNMB may represent a novel multi-target therapeutic approach to treat neurodegenerative diseases, including PD." (PMID 29519253, 2018). "Further studies are necessary to understand the contribution of GPNMB and galectin-3 to FTD and related neurodegenerative disease." (PMID 33028409, 2020). "Glycoprotein Non-Metastatic Melanoma Protein B (GPNMB), a transmembrane glycoprotein, has recently emerged as a critical player in neurodegenerative diseases." (PMID 40367036, 2025). "Given the involvement of GPNMB in other neurodegenerative diseases besides AD, it is unlikely to serve as a disease-specific biomarker." (PMID 30340518, 2018). "However, GPNMB is not a specific biomarker for AD; overexpression of this protein was also observed in other neurodegenerative diseases, such as ALS and PD." (PMID 37510803, 2023). "Thus, maintaining GPNMB expression in glaucomatous RGCs could halt RGC death and optic nerve degeneration, and GPNMB could be a common therapeutic target enhancing neuroprotection and axon regeneration in neurodegenerative diseases and after nerve injury." (PMID 34735454, 2021).
neurological diseases (9 papers, 2017 to 2023). "Elevated expressions of GPNMB in cerebrospinal fluid in the brain have been considered as possible biomarker candidates for several neurological diseases, such as ALS." (PMID 37786733, 2022). "Seven of these proteins have cis-acting pQTLs that colocalise with or are causal for neurological diseases: DDR1, IL12, NEP, CD33, DPEP1, GPNMB, and LEPR." (PMID 34857772, 2021). "It is known that GPNMB plays a crucial role in different kinds of neurological diseases." (PMID 37786733, 2022). "Interestingly, of these five highly elevated proteins, only GPNMB and NfL in CSF have previously been shown as biomarkers in neurological disease." (PMID 35269535, 2022). "We identified PGRN as an important regulator of immune cell activation in central and peripheral compartments, where GPNMB is potentially involved, suggesting that PGRN and GPNMB could be relevant targets for neurological diseases with an immunological component." (PMID 36618392, 2022). "Relative to non-neurological disease (NND) controls, Neuro-HIV brains showed an increase in GPNMB + IBA1 + cells in the brain." (PMID 38037070, 2023). "Given that the extracellular domain of GPNMB can be shed as an extracellular soluble fragment (ECF), it is a potential biomarker candidate for neurological disease, including AD, but different groups disagree as to whether GPNMB is a reliable biomarker of disease progression." (PMID 38037070, 2023). "The results indicated that CSF GPNMB levels could not distinguish between AD or controls with other neurological diseases but correlated with other parameters such as aging and CSF pTau levels." (PMID 33947460, 2021).
infection (7 papers, 2018 to 2026). The state of being infected such as from the introduction of a foreign agent such as serum, vaccine, antigenic substance or organism. "During infection, GPNMB bound to autophagosomal-localized STX17, leading to the deglycosylation of GPNMB, which promoted SNAP29 degradation." (PMID 40038549, 2025). "In the case of porcine reproductive and respiratory syndrome virus (PRRSV) infection, GPNMB inhibits viral replication by preventing autophagosome‒lysosome fusion." (PMID 40038549, 2025). "CD44 blockade also markedly decreased GPNMB+CD11c+ and F4/80+ macrophage infiltration at 49 days after infection." (PMID 39052353, 2024). "Glycoprotein nonmetastatic melanoma protein B (GPNMB) has been implicated in regulating cellular functions, particularly within the vasculature during inflammation, but its effect on infection-mediated endothelial injury remains unclear." (PMID 41492208, 2026). "After infection for 6 h, GPNMB colocalized with M. leprae in the LC3+ or p62+ cytoplasmic puncta." (PMID 40038549, 2025). "Therefore, we concluded that the deglycosylation of N296 by GPNMB may inhibit xenophagy and promote bacterial survival during infection." (PMID 40038549, 2025). "Similarly, GPNMB protein was colocalized in lung tissue to CD11c+ cells with primarily moDC morphology at early time points (12 days) and then also alveolar macrophage appearance at late time points (49 days) after infection." (PMID 39052353, 2024). "Thus, we speculated that GPNMB is likely to move to autophagosomes during infection." (PMID 40038549, 2025). "Upon infection, GPNMB interacts with autophagosomal-localized STX17, leading to a reduced N-glycosylation level at N296 of GPNMB." (PMID 40038549, 2025). "As done for GPNMB, we determined CD44 function in vivo using anti-CD44 mAb treatment in the SeV mouse model with dosing at 5–14 days after infection." (PMID 39052353, 2024). "After infection with PRRSV, we observed that viral replication was decreased in GPNMB-overexpressing PAMs compared to the vector control." (PMID 37112900, 2023). "In GPNMB-overexpressed cells, PCV2 genome and ORF5 RNA expression were significantly decreased at 24 and 48 h post-infection, as compared with control." (PMID 30671053, 2018). "The GPNMB functions to reduce inflammation by increasing anti-inflammatory cytokines like IL10 and decreasing proinflammatory cytokines like TNFα, IL-6, and IL-12, which aid in response to lesions in the tissue or infection, and can be triggered by pathogens that are present in their environment." (PMID 39744066, 2024).
metabolic disorders (6 papers, 2021 to 2025). "Deteriorated WAT inflammation associated with augmented macrophage infiltration is causally involved in the exacerbated metabolic disorders in male obese GPNMB-KO mice." (PMID 34582891, 2021). "Finally, we showed that macrophage depletion by addition of clodronate liposomes abolished the worsened WAT inflammation and abrogated the exacerbation of metabolic disorders in GPNMB-deficient mice fed on HFD." (PMID 34582891, 2021). "Our previous data along with other recent studies have demonstrated increased circulating levels of GPNMB in those with metabolic diseases." (PMID 38790981, 2024). "Subjects in the highest GPNMB tertile group were more likely to have metabolic disorder, cataract, and DM." (PMID 36875463, 2023). "Of note, exacerbated metabolic disorders in GPNMB-KO mice were abolished by administrating clodronate liposomes." (PMID 34582891, 2021). "Levels of GPNMB have been shown to be increased in various metabolic disorders." (PMID 38790981, 2024).
breast (2 papers, 2020 to 2021). "In this study, we found that GPNMB expression in serum, cerebellum, and liver was decreased, accompanied by the attenuation of Purkinje cell loss and liver dysfunction by intracerebroventricular HP-β-CD treatment." (PMID 33466390, 2021).
adenocarcinoma (1 paper, 2018). A common cancer characterized by the presence of malignant glandular cells. "Also, there was an association between the increase of GPNMB methylation and the potential for progression to invasive stage adenocarcinomas." (PMID 30400781, 2018).
bacterial infection (1 paper, 2025). "In this study, we found that GPNMB suppressed the production of proinflammatory cytokines upon bacterial infection." (PMID 40038549, 2025). "Upon bacterial infection, GPNMB is recruited to autophagosomes through interaction with STX17, disrupting the assembly of the STX17-SNAP29-VAMP8 SNARE complex." (PMID 40038549, 2025). "In this study, we revealed that GPNMB inhibited host defense against intracellular bacterial infection by disrupting the fusion of autophagosomes with lysosomes." (PMID 40038549, 2025). "Deglycosylation of GPNMB at residue N296 led to the degradation of SNAP29 upon bacterial infection." (PMID 40038549, 2025). "In addition to Mycobacterium leprae, GPNMB deficiency impairs the proliferation of various intracellular bacteria in human macrophages, suggesting a universal role of GPNMB in intracellular bacterial infection." (PMID 40038549, 2025). "Moreover, the binding of GPNMB with STX17 was enhanced upon bacterial infection." (PMID 40038549, 2025). "Taken together, our data revealed that GPNMB blocked cellular autophagic flux by disrupting the interaction between STX17 and SNAP29 during bacterial infection." (PMID 40038549, 2025). "We found that GPNMB blocked the assembly of the STX17-SNAP29-VAMP8 SNARE complex, thereby inhibiting autophagosome maturation during bacterial infection." (PMID 40038549, 2025). "However, the role of GPNMB in the host defense against bacterial infection remains unclear." (PMID 40038549, 2025). "In conclusion, our study revealed a negative role of GPNMB in regulating xenophagy upon bacterial infection." (PMID 40038549, 2025).
kidney disease (1 paper, 2020). "However, in the present study, GPNMB mRNA expression in the urinary sediment modified the slope of eGFR in T1D patients across time, maybe reflecting a compensatory mechanism of tissue repairing as kidney disease progresses." (PMID 32425885, 2020).
GPNMB also shares sentences with these, for which no sentence is quoted: polycystic kidney disease (4 papers); Niemann-Pick disease type C (3); non-small cell lung carcinoma (3); schizophrenia (3); esophageal squamous cell carcinoma (2); frontotemporal dementia (2); Adult onset (1); alcoholic steatohepatitis (1); Anaplastic Thyroid Carcinoma (1); B-cell non-Hodgkin lymphoma (1); Birt-Hogg-Dube syndrome (1); bladder tumour (1); brain disorder (1); carbon monoxide poisoning (1); cardiovascular diseases (1); Creutzfeldt Jakob disease (1); dermatomyositis (1); diffuse large B-cell lymphoma (1); dilation (1); Encephalopathy (1); end-stage renal disease (1); Ewing sarcoma (1); familial Alzheimer disease (1); Fibroadenoma (1); fibrosarcoma (1); fibrosis (1); gastrointestinal disorders (1); Gaucher disease type 3 (1); Glucose intolerance (1); Granuloma (1).
A further 37 diseases each share a sentence with GPNMB in 1 paper.